ALAS2 (5'-aminolevulinate synthase 2)
Diseases named in the same sentence as ALAS2 in open-access papers (continued):
Sharing a sentence is not in itself a finding about the gene and the disease.
infection (5 papers, 2013 to 2025). The state of being infected such as from the introduction of a foreign agent such as serum, vaccine, antigenic substance or organism. "Heme/hemoglobin metabolism was enriched in groups 1, 2, and 4, with four common genes (ALAS2, AHSP, HBD, and CA1) that are associated with the immune response to infection." (PMID 41839673, 2025). "In the bone marrow, the mRNA expression of erythroid differentiation genes (α-globin, β-globin, ALAS2) were inhibited by 50%, but mRNA levels of erythroid receptor (c-kit, EpoR) and transcription factors (GATA1, GATA2, FOG1) were not affected by the infection." (PMID 23533629, 2013).
blood disorders (3 papers, 2018 to 2024). "However, the recent crystal structure of human ALAS2 provides insight into how this gatekeeper functions for optimal heme production but also how mutations lead to various blood disorders." (PMID 35093382, 2022).
metabolic disorder (1 paper, 2022). "Remarkably, however, loss-of-function mutations are not the only cause of ALAS2-associated metabolic disorder." (PMID 35911972, 2022). "This prediction was subsequently supported by the discoveries that mutations in the extended C-terminus of the erythroid ALAS isoform (ALAS2) cause a metabolic disorder known as X-linked protoporphyria not by diminishing activity, but by enhancing it." (PMID 35911972, 2022).
ALAS2 also shares sentences with these, for which no sentence is quoted: cardiomyopathy (2 papers); hereditary spherocytosis (2); iron overload (2); macrocytic anemia (2); Alzheimer disease (1); Atrophy (1); Bartter syndrome (1); breast carcinoma (1); Cachexia (1); cardiovascular disease (1); colorectal cancer (1); congenital anemia (1); Congenital hemolytic anemia (1); depression (1); erythroleukemia (1); heart failure (1); hemochromatosis (1); hereditary sideroblastic anemia (1); hereditary thrombocytopenia (1); hydrops (1); Macrothrombocytopenia (1); metastatic tumor (1); muscular disease (1); necrotizing enterocolitis (1); neuropathic pain (1); sitosterolemia (1); Thrombocytosis (1); X-linked disease (1).